IGF1R (insulin like growth factor 1 receptor)
Diseases named in the same sentence as IGF1R in open-access papers (continued):
Sharing a sentence is not in itself a finding about the gene and the disease.
diabetes (continued). "In the pre-diabetes stage, the interruption of IGF-1R signaling in the muscles and fat tissue, the primary tissues involved in the glucose metabolism will lead to insulin resistance and progression to DM." (PMID 31847392, 2019). "Growth factor signaling via insulin receptor (IR) and IGF-1 receptor (IGF1R) plays several important roles in the pathogenesis of metabolic syndrome and diabetes." (PMID 28646158, 2017). "In an experimental model, transgenic mice expressing a kinase-deficient IGF-1R β-subunit (thus displaying reduced signal transduction in both IGF-1R and hybrid receptors) developed diabetes early on life." (PMID 26733412, 2016). "Cardiac overexpression of IGF-1R prevented diabetes-induced cardiac fibrosis and diastolic dysfunction." (PMID 27027354, 2016). "The cardiac protection from diabetes, including anti-inflammation and anti-apoptosis, was found to be partly mediated by activation of IGF-1R/Akt pathway." (PMID 27027354, 2016). "In the early days of growth factor and oncogene research, in 1988, a 22-year long study commenced following a particularly interesting group of patients, to investigate the role of IGF-1R in aging, diabetes and cancer development." (PMID 25964779, 2015). "In ERMs, IGF1 and IGF1R mRNA levels were significantly higher in patients with diabetes compared to control subjects." (PMID 24379526, 2013). "The effect of diabetes on mRNA expression at each time point varied among IGF1R, IGFBP1, IGFBP2, and IGFBP3." (PMID 23878504, 2013). "Circ‐IGF1R functioned in ADSC‐HEV‐mediated wound repair in mice with diabetes." (PMID 38984951, 2024). "Additionally, since insulin and IGF-1 are functionally intertwined, the profound consequences of diabetes on insulin function heavily affect IGF-1/IGF-1R activity, and vice versa." (PMID 39638246, 2024). "However, diabetes is associated with an increased cancer risk, explained by insulin-like growth factor 1 (IGF-1), IGF-1R, and the signaling pathway." (PMID 38774165, 2024). "IGF1R rs6598541 was reported to be genome-wide associated with fasting glucose: people without diabetes carrying the A-allele have increased fasting glucose levels, suggesting an association with insulin resistance." (PMID 38347000, 2024). "In addition, the high-scoring functions in the pathways were the insulin-like growth factor 1 receptor (IGF1R) and the diabetes mellitus pathway with subsequent inhibition of the PI3K/Akt pathway involved in glucose import." (PMID 36769365, 2023). "Therefore, the collective indication of these studies and the present study indicate a significant correlation between the IGF1R signaling pathway and disruption in glucose metabolism leading to diabetes." (PMID 38274107, 2023). "Epigenetic regulation of IGF1R has also been examined in animal models of diabetes." (PMID 35500004, 2022). "This suggests that MAO activation in diabetes might impact the activation of signaling pathways downstream of Igf1r via miRNA modulation." (PMID 36078109, 2022). "Furthermore, INS and IGF1R, predicted targets of KXS in AD therapy, are also associated with diabetes." (PMID 35303280, 2022). "Thus, transgenic mice expressing a kinase-deficient IGF1R β-subunit with reduced signal transduction in both IGF1R and IGF1R/InsR hybrid receptors developed diabetes early on life." (PMID 36353242, 2022). "Recent studies have reported that the abnormal glucose metabolism, insulin resistance, and the activation of the IGF/insulin-like growth factor-1 receptor (IGF-1R) signaling axis in diabetes contribute to the genesis, growth, proliferation, and metastases of intraocular malignancy." (PMID 36003786, 2022). "Heterozygous mutations in the IGF1R gene, causing partial resistance to IGF1, are associated with several metabolic and endocrine alterations such as hypo/hyperlipidemia, hypothyroidism, diabetes/insulin resistance or even hypoglycaemia." (PMID 36353242, 2022). "Diabetes affects IGF1/IGF1R expression and signaling in several organs." (PMID 33575847, 2021).
diabetes (continued). "Our previous studies reported that berberine could reduce ischemia/reperfusion-induced myocardial apoptosis, improve mesenteric artery insulin sensitivity in diabetes, and reduce diabetic myocardial damage by inhibiting IGF-1R signaling." (PMID 35008753, 2021). "The aim of the present study was to measure the content of IR and IGF-1R and their phosphorylation in the placenta of women with type 1 diabetes mellitus (T1D) or with gestational diabetes mellitus (GDM) compared to women with normal glucose tolerance (NGT) during pregnancy." (PMID 33776919, 2021). "In addition, tofogliflozin (sodium-glucose cotransporter 2 inhibitor) is the drug used to treat T2DM and it reduces the risk of CRC through attenuation of chronic inflammation, hyperglycemic state and IGF/IGF-1R axis activation in obesity and diabetes mice." (PMID 32210144, 2020). "However, the high level of IGF1R transcript in foetal heart and liver of pregnancy diabetes rats relative to controls was augmented." (PMID 33085184, 2020). "We hence speculate that hyperinsulinemia, that is associated with type 2 diabetes mellitus, promotes RCC progression through enhanced signaling of IGF1R and PI3K in cancer cells." (PMID 31815952, 2019). "Tamoxifen, but not aromatase inhibitors, increases the risk for diabetes and an in vivo study suggests that tamoxifen is associated with lower total IGF1R levels but higher phosphorylated IGF1R levels." (PMID 29928262, 2018). "IGF1R and mTOR inhibitors might interfere with glucose metabolism and iatrogenic diabetes has been reported as side effect of IGF1R inhibitors." (PMID 29486734, 2018). "Even if we could specifically block the IGF-1R and not IR, unwanted effects may arise such as glucose dysregulation and diabetes due to the inhibition of hybrid IGF-1R/IR receptors." (PMID 25743390, 2015). "Similar changes in IGF1R signaling have been described in diabetes, suggesting that decreased IGF1/IGF1R signaling might be involved in the pathogenesis of both diabetes and AD." (PMID 25268761, 2014). "Previous studies have demonstrated that the expression level of IGF1 and IGF1R decreased in brain tissue of diabetes, and disruption of the GIGYF2 gene in mice led to a decrease in IGF1-stimulated IGF1R tyrosine phosphorylation but an augmentation in ERK1/2 phosphorylation." (PMID 25268761, 2014). "Thus, FoxOs may also regulate muscle strength by controlling calcium signaling genes, and open avenues to study the mechanisms how IR/IGF1R and FoxO axis regulate calcium homeostasis in diabetes-related muscle atrophy." (PMID 35185597, 2021). "Likewise, it will be relevant to identify the role of paralogs and/or alternatively spliced mTOR intrinsic regulatory components in its two major cellular complexes—mTORC1 (Raptor-driven) and mTORC2 (Rictor-driven) —towards affecting the IR/IGF1R signaling in obesity/diabetes and cancer." (PMID 33266015, 2020). "Rats with streptozotocin-induced diabetes were randomly divided into four groups and treated with different doses of vitamin D3: no vitamin D3, low (0.025 μg/kg/day), high (0.1 μg/kg/day), and high (0.1 μg/kg/day) with JB-1 (the insulin-like growth factor-1 receptor inhibitor group, 100 μg/kg/day)." (PMID 31281852, 2019). "Our findings suggest that GIGYF2 may play an important role in the development of diabetes-associated cognitive impairment through modulating the phosphorylation of IGF1R and its downstream ERK1/2 signaling pathway, but not Akt signaling pathway." (PMID 25268761, 2014). "However, the pathophysiological function of GIGYF2, particularly its role in the aberrant IGF1R signaling pathway in diabetes, remains largely unknown." (PMID 25268761, 2014). "Similarly, Nelfinavir is predicted to inhibit IGF-1R, which regulates the insulin/insulin-like growth factor signaling pathway, and offers one possible explanation for the observed side effects of Nelfinavir on insulin resistance and diabetes." (PMID 21552547, 2011).
diabetes (continued). "The research by Wang and colleagues showed that miR-503 from M1 macrophage-released EVs inhibits insulin-like growth factor 1 receptor (IGF1R) expression in HUVECs, thereby impeding the wound healing process in individuals with diabetes." (PMID 39439564, 2024). "The diabetes-related histological and functional changes, as well as fibrogenesis, can be attenuated by IGF-1/IGF-1R inhibition." (PMID 38375323, 2024). "Studies in CRC patients with diabetes mellitus (DM) (n = 125) showed a positive correlation between IGF-1, IGF-1R and IR expressions in all cancer tissues." (PMID 36835075, 2023). "As a result, IRS-related signaling by IGF1R, which is directly related to diabetes, was derived (IRS2, IGF1R, PIK3CD, and PIK3CB)." (PMID 37608331, 2023). "This review explores the novel anticancer agents targeting IGF-1R and receptor for advanced glycation end products (RAGE), both of which play a vital role in diabetes-induced colorectal tumorigenesis." (PMID 35296101, 2022). "Inhibitors of IGF-1R and RAGE are expected to become promising therapeutic choices, particularly for CRC patients with diabetes." (PMID 35296101, 2022). "Our results delineated a link between MAOs, ROS, miR-133a-3p and Igf1r, suggesting that MAO activity in diabetes leads to an upregulation of miR-133a-3p that, in turn, results in the degradation of Igf1r mRNA." (PMID 36078109, 2022). "An in vivo study using a transgenic mouse model characterized by a dominant-negative IGF-1R specifically targeted the skeletal muscle (KR-IGF-1R) demonstrated glucose intolerance at 8 weeks of age and overt diabetes at 12 weeks of age." (PMID 34685644, 2021). "Collectively, these results show that the effects of diabetes and high glucose on IGF1/IGF1R expression are tissue-specific." (PMID 33575847, 2021). "After stratification for menopause, we noticed that the direction of the effects of diabetes on p-ER, p-ERK1/2 and IGF1R differed in pre- and postmenopausal women." (PMID 29486734, 2018). "Thus, identification of therapeutics that bias the IGF-1R to selectively activate Akt would address potential concerns that IGF-1 may exacerbate microvascular dysfunction in diabetes through ERK, as it can also play a role in VEGF-induced RNV since IGF-1-induced VEGF expression is ERK-dependent." (PMID 28796787, 2017). "Insulin and insulin-like growth factor-1 (IGF-1) signaling, by IGF-1R, are differentially involved in keratinocyte differentiation, promoting the inhibition of normal keratinocyte differentiation, suggesting that abnormal insulin signaling, as what occurs in diabetes, may lead to skin pathology." (PMID 27840833, 2016). "Catalpol treatment could improve diabetes-associated impaired renal functions and ameliorate pathological changes in diabetic kidneys, while such beneficial effects correlate with a down-regulation of Grb10 expression and a concomitant up-regulation of IGF-1/IGF-1R signaling in diabetic kidneys." (PMID 26986757, 2016). "We show that among the five insulin analogues presently used to treat diabetes, only glargine displays a significantly higher potency than insulin in stimulating IRA/IGF1R and IRB/IGF1R." (PMID 22848683, 2012). "Understanding the mechanism of IR and IGF-1R activation is critical for the future design of insulin mimetics and inhibitors of IGF action for the treatment of diseases such as diabetes and cancer." (PMID 22140443, 2011). "However, overexpression of circ‐IGF1R increased HK2 and VEGFA expression, and HEV treatment ulcerated tissue in mice with diabetes." (PMID 38984951, 2024). "We conclude that GRP94 plays an essential role in stress-induced β cells, at least in part via regulation of IGF-1R, and that dysfunction of GRP94 may contribute to the development of diabetes and diabetes complications." (PMID 38811543, 2024).
diabetes (continued). "We also identified a new client of GRP94, insulin-like growth factor-1 receptor (IGF-1R), a critical factor for β cell survival and function that may mediate the effect of GRP94 in the pathogenesis of diabetes." (PMID 38811543, 2024). "The phenotype of diabetes by blocking IGF-1 signaling is more obvious in mouse models lacking both IGF1R and INSR in β-cells." (PMID 35370981, 2022). "Prevention of diabetes and treatments targeting abnormal glucose metabolism, IGF-1/IGF-1R signaling axis, and insulin resistance may provide novel opportunities to improve prognosis and delay the lethal metastases of intraocular malignancies." (PMID 36003786, 2022). "In the human retina, diabetes decreases IGF1 expression and promotes a slight increase in IGF1R." (PMID 33575847, 2021). "In vivo studies support this hypothesis, because β-cell–specific knockout of IR, IGF1R, or AKT induced fasting hyperinsulinemia and diabetes." (PMID 32934005, 2020). "Using a murine model of vascular injury, we show that calpeptin restores the platelet expression of miR-223 in diabetes, and the horizontal transfer of platelet miR-223 into VSMCs inhibits VSMC proliferation in the injured artery by targeting the expression of IGF-1R." (PMID 32733269, 2020). "Deleterious IR/IGF1R signaling or altered FA composition and function may lead to fasting hyperinsulinemia and a decrease of GSIS observed in the physiopathology of diabetes." (PMID 32934005, 2020). "In murine model of vascular injury, we show that calpeptin restores the platelet expression of miR-223 in diabetes, and the horizontal transfer of platelet miR-223 into VSMCs inhibits VSMC proliferation in the injured artery by targeting the expression of IGF-1R." (PMID 32733269, 2020). "There is a (small) chance that our findings are subject to confounding by indication; severe diabetes and not insulin is related with increased p-mTOR and IGF1R expression." (PMID 29486734, 2018). "We found no strong evidence that p-ER, EGFR, p-ERK1/2, p-mTOR, or IGF1R are differently expressed in breast tumors of women with and without diabetes." (PMID 29486734, 2018). "In our material women with EC and diabetes demonstrated a significantly higher IGF-1R expression in comparison to the non-diabetic women." (PMID 24308813, 2013). "Cancer patients with diabetes showed a significantly higher IGF-1R expression then the non-diabetic group (p = 0.0012)." (PMID 24308813, 2013). "Moreover, the diabetes-related histological and functional changes, especially fibro-genesis, could be attenuated by IGF-1/IGF-1R inhibitors." (PMID 38375323, 2024). "In the current study, STZ-induced diabetes did not change significantly cardiac IGF-1R expression." (PMID 37851320, 2023). "Insr and Igf1r mRNA contents were not changed by diabetes in either tissue." (PMID 33915127, 2021). "Similarly, anti-PDGFRB and anti-IGF1R therapy in COVID-19 patients with or without pre-existing diabetes require further investigations." (PMID 34067609, 2021). "Moreover, miR-25 level was higher in SVEC of patients with diabetes, and, importantly, when we transfected SVEC from patients without diabetes with mutant IGF-1R, miR-25 expression was significantly reduced with a reciprocal increase in the Nox4 expression." (PMID 34420367, 2021). "Finally, we assessed a model of nonobese diabetes, i.e., transgenic mice expressing a mutant dominant-negative insulin-like growth factor-1 receptor (KR-IGF-1R) specifically targeted to skeletal muscle (MKR mice)." (PMID 33148881, 2020). "Since Grb10 has been demonstrated to negatively regulate IGF-1/IGF-1R signaling, we then determined whether catalpol-mediated down-regulation of Grb10 expression was coupled to up-regulation of IGF-1/IGF-1R signaling in diabetic kidneys." (PMID 26986757, 2016). "Diabetes did not alter the mRNA expression of IGF1R or IGFBP1 (p>0.15)." (PMID 23878504, 2013).
diabetes (continued). "Therefore, NPC43, through its interaction with INSRα and selective activation of INSR but not IGF1R, may represent a novel oral, safe and effective agent for the treatment of diabetes in humans." (PMID 31378829, 2020). "Mice lacking IGF1R and INSR in adipocytes contain almost no adipose tissue and develop significant diabetes, dyslipidemia, and fatty liver." (PMID 35370981, 2022). "Diabetes increased the expression of IGFBP2 after 12 weeks and IGFBP3 after 4 and 12 weeks, but did not change the expression of IGF1R or IGFBP1." (PMID 23878504, 2013).